IL2 (interleukin 2)
Diseases named in the same sentence as IL2 in open-access papers (continued):
Sharing a sentence is not in itself a finding about the gene and the disease.
parasitemia (40 papers, 2011 to 2025). "Blocking of IL-2 during the acute T. cruzi infection by using a neutralizing monoclonal antibody resulted in lower parasitemia and mortality of treated animals." (PMID 39119291, 2024). "Different haplotypes of IL6 gene or IL6R genes have been related to IL-6 and other cytokine serum levels in humans, including IL-2, IL-8 and IL-18 cytokines, and with the severity or protective effect of the infectious disease, including parasitic diseases." (PMID 36759910, 2023). "At day 4 p.i. in baso (−) mice, 16S copy numbers were directly and weakly negatively correlated with plasma IL-2 and IL-3, whereas parasitemia was weakly correlated with plasma MCP-1 (negatively) and ileal MIP-1α (positively)." (PMID 35970557, 2022). "As mentioned in studies, in the early stages of CE, a Th1 immune response dominates to protect from parasite infection by secreted IL-2, IFN-γ, TNF and so on." (PMID 35360110, 2022). "C57Bl/6 mice treated with blocking mAb to IL-2, starting one day before infection, presented lower parasitemia on the 28th day than mice treated with rat Ig as a control." (PMID 34869064, 2021). "T cells have also been considered as unresponsive to secrete IFNγ and IL2 cytokines under T. cruzi antigens stimulation in a murine model of infection with parasite and leukemia virus, associated with CDR and higher parasitemia." (PMID 34591866, 2021). "Alkaloids treatment (SAT group and SAT + AT group) significantly stimulated expression of these complement activation-associated proteins and enhanced host immune response against parasite infection by increasing IL-2 and IL-10 level in serum." (PMID 29785189, 2018). "We found increased GRAIL expression at the early stages of infection, coinciding with the peak of parasitemia, with these findings correlating with impaired proliferation and poor IL-2 and IFN-γ secretion in response to plate-bound antibodies." (PMID 28114324, 2017). "Parasitemia was significantly correlated with the following cytokines, in order of strength of association: IL-10, IL-12, TNF-α, IFN-γ, IL-1β, IL-6, IL-5, IL-2, IL-4, and IL-7." (PMID 27418744, 2016). "Our study demonstrated that infection with the nahG-transfectant induced upregulation of proinflammatory cytokines including IFN-γ, IL-1β, IL-2, and IL-12, while parasitemia and hematocrit were almost uniform at the same time point." (PMID 26466097, 2015). "We identified and investigated regulatory polymorphisms in the immune gene IL2 and its receptor IL2R alpha (also known as CD25) in Gabonese individuals exposed to plentiful parasitic infections." (PMID 23217119, 2012). "In the current study, our goal is to identify regulatory single nucleotide polymorphisms (SNPs) in the promoter region of the IL2 and its receptor IL2R alpha (CD25) gene loci in a Sub-Saharan African population exposed to a wide array of parasitic diseases." (PMID 23217119, 2012). "In our study, malaria infections were shown to significantly decrease the frequency of CD4 and CD8 triple positive MFT cells expressing IFN-γ, TNF-α, and IL-2 in lung cells of BCG vaccinated mice when high levels of parasitemia were present." (PMID 22205939, 2011). "Notably, previous studies have reported that the multifunctional Th1 cells simultaneously expressing IFN-γ, TNF-α and IL-2 correlated best with the degree of protection of vaccine models against parasite infection." (PMID 35812841, 2022). "Th1 subsets mainly express IFN-γ and IL-2, which are involved in cellular immunity to endogenous cell infection, while Th2 subsets express IL-4 and IL-10, which participate in allergic reactions and humoral immunity against parasitic infection." (PMID 36425118, 2022). "The results show that parasitemia and mortality rate was lower in mice treated with anti-IL-2." (PMID 34869064, 2021). "This treatment resulted in lower parasitemia and lower mortality of anti-IL-2 treated mice." (PMID 34869064, 2021).
parasitemia (continued). "The results show that parasitemia and mortality rate was lower in animals treated with anti-IL-2." (PMID 34869064, 2021). "Th1 cells mainly secrete cytokines such as IFN-γ and IL-2, which play an important role in antiviral and bacterial immune responses, while Th2 cells mainly secrete cytokines such as IL-4 and IL-10, which play a role in parasitic infection." (PMID 33294465, 2020). "Therefore, IL-2 withdrawal favours the collapse of regulatory response and the development of pathology, while the treatment of mice with IL-2 plus glucocorticoids or an IL-2-anti-IL-2 complex can improve Treg response following parasite infection." (PMID 26745276, 2016). "The assessment of correlations between each of the cytokines/chemokine and parasitemia showed that IL-2 and IFN-γ levels were independent from parasitemias, suggesting that other mechanisms could play a role in regulating those TH1 cytokines." (PMID 23967342, 2013). "Furthermore, IFN-γ and IL-2 are important stimulatory cytokines involved in the protection against parasitic infection." (PMID 22837100, 2012). "However, the role of the described and novel variants of IL2 and IL2R alpha in this study needs to be validated in terms of the specific role these play in different parasitic diseases." (PMID 23217119, 2012). "The phenomenon of T-cell exhaustion, which can be seen in advanced disease, features low IL-2 levels alongside high IL-10 and TGF-β production by lymphocytes, as described in other viral and parasitic diseases." (PMID 40909167, 2025). "Eotaxin was positively correlated with NE and plasma RANTES (CCL5), IL-1α, and IL-2, and strongly negatively correlated with MPO, Mcpt1, parasitemia, plasma IL-4, ileal MCs, and FITC-dextran." (PMID 38780542, 2024). "It was confirmed that cytokines such as IL-12, TNF-α, IFN-γ, and IL-2 play an important role in controlling the proliferation of Babesia in the early and acute stages of infection, while IL-10, IL-4, IL-5, and IL-6 may involve in chronic and low parasitemia stages of infections." (PMID 32733477, 2020). "Th1 cells play an important role in host defense against intracellular parasitic infections, promoting the activation and proliferation of cytotoxic lymphocytes, natural killer cells and macrophages via the production of IFN-γ, TNF-β and IL-2." (PMID 26230498, 2015). "For instance, γδ T cells showed a Th1 effect by generating IL-2 and INF-γ when bacterial infection occurred inside cells; but showed a Th2 effect by stimulating B cells with IL-4 and IL-5 with extracellular parasite infection." (PMID 24460842, 2014). "However, the expression of IL-2, IL-12, IFN-γ, together with that of specific transcriptional factors (STAT1 and STAT4) is suggestive of a Th1-like polarization, induced after parasite infection." (PMID 35632559, 2022). "As parasitemia worsened from days 0 to 7, the concentrations of IL-12p70, IL-10, and IL-4 in the supernatant increased in the BMSA vaccinated group, although the concentrations of IL-2, IFN-γ, and IL-17 decreased." (PMID 29312230, 2017). "Therefore, it is possible that T cell hyporesponsiveness caused by T. cruzi antigens such as mucins, and characterized by decreased IL-2 synthesis, might be mediated by GRAIL since expression of this E3 Ubiquitin Ligase correlates with the peak of the parasitemia." (PMID 28114324, 2017).
periodontitis (40 papers, 2014 to 2025). An acute or chronic inflammatory process that affects the tissues that surround and support the teeth. "In a recent meta-analysis, though, a non-significant association between 330 T/G polymorphism in the IL2 gene and chronic periodontitis, in any allelic evaluation, was reported." (PMID 35454140, 2022). "The IL-2 −330G allele had a weak relationship with the periodontitis development (OR: 0.96; 95% CI: 0.72–1.20)." (PMID 35454140, 2022). "Other clinical and animal studies reported enhanced serum levels for IFN-γ, TNF-α, and IL-10, as well as decreased IL-2 levels in patients with A. actinomycetemcomitans- and P. gingivalis-associated periodontitis." (PMID 35203495, 2022). "In contrast, the IL-2 −330T allele had a strong relationship with the periodontitis risk (OR: 0.85; 95% CI: 0.35–1.24)." (PMID 35454140, 2022). "In contrast, IL-2 −330T allele had a strong relationship with the periodontitis risk with OR (95% CI), 0.80 (0.35–1.24)." (PMID 35046930, 2021). "IL-2 −330G allele had a weak relationship with the periodontitis development with OR (95% CI), 0.96 (0.72–1.20)." (PMID 35046930, 2021). "Differently, in Chinese, IL2–330 G allele and G/G genotype were a risk for periodontitis and were linked to higher levels of the IL-2 in the serum of these patients." (PMID 31978095, 2020). "The meta-analysis calculations showed a non-significant association between the − 330 T/G polymorphism in IL2 gene and periodontitis in the ethnical evaluation." (PMID 32075624, 2020). "Taken the IL-2 and periodontitis, there are contradictory findings available in the literature that regarding the association between increased IL-2 levels and the disease." (PMID 32075624, 2020). "The polymorphisms in NLRP3, IL1B and IL2 genes influence the development of periodontitis, independently of smoking habits." (PMID 31978095, 2020). "Recent advances in IL‐2‐based therapies involve engineered IL‐2 variants that selectively target Tregs, providing a promising avenue for developing Treg‐based therapies in chronic inflammatory conditions like periodontitis." (PMID 41399014, 2025). "Although, to the best our knowledge, this is the first meta-analysis to focus in to determinate the association between a polymorphism in IL2 gene and periodontitis and brought significant number of participants, the meta-analysis showed important limitations that should be noted." (PMID 32075624, 2020). "IL-2 is predominantly secreted by Th1 cells, and recent research posits that genetic polymorphisms in IL-2 may be linked to the pathogenesis and prevention of periodontitis." (PMID 39830512, 2024). "Similarly, the plausible mechanisms explaining the association between low salivary flow rate and periodontitis might be due to also the increased proinflammatory cytokine levels, such as IL-2, IL-17, and TNF, triggering glandular damage and hyposalivation." (PMID 37408223, 2023). "In the context of periodontitis, the administration of low‐dose IL‐2 has been proposed as a potential therapeutic strategy to boost Treg populations and restore immune homeostasis, thereby controlling excessive inflammation and bone resorption." (PMID 41399014, 2025). "We evaluated the effects of ω-3 PUFA on the cytokines TNFα, IL-2, IFNγ, IL-4, and IL-5 in a P. gingivalis ligature-induced periodontitis in the serum of mice." (PMID 37378834, 2024). "The pro-inflammatory cytokines TNF-α and IL-6 were increased in the APDC-KO mice after 3 weeks of periodontitis induction, whereas the pleiotropic cytokine IL-2, which mediates both pro- and anti-inflammatory functions, was significantly decreased." (PMID 37928259, 2023). "The expression of Il-2 tended to be downregulated in Spock1-Tg mice at basal and increased by experimental periodontitis in both WT and Spock-1Tg mice." (PMID 38156070, 2023).
periodontitis (continued). "Fusobacterium positively correlated with IFN-γ, IL-12p70, and IL-2 and is known to be enriched in periodontitis as an important component of periodontal biofilms (47, 54, –, 57)." (PMID 35189698, 2022). "Accordingly, we locally delivered a combination of TGFβ, Rapamycin, and IL2 microspheres in a ligature-induced murine periodontitis model." (PMID 35322204, 2022). "IL-2 is a pro-inflammatory cytokine, produced, inter alia, by lymphocytes isolated from periodontal tissues, collected from patients with chronic periodontitis." (PMID 35454140, 2022). "In a case-control study, the higher frequencies of the IL2 (+166, −330) haplotype were observed in patients with chronic periodontitis, when compared to controls of a mixed population." (PMID 35454140, 2022). "Oral blood mononuclear cells (OBMCs), and peripheral blood mononuclear cells (PBMCs) of periodontitis patients and healthy individuals were left untreated, or treated with IL-2 or PMA plus ionomycin (PMA/I) overnight." (PMID 33672708, 2021). "When added to IL-2-activated allogeneic PBMCs, supernatants obtained from OBMCs of periodontitis patients were only able to increase IFN-γ secretion by about 2.4-fold, whereas those obtained from healthy individuals increased by 5.4-fold." (PMID 33672708, 2021). "OBMCs and PBMCs of periodontitis patients were left untreated or treated with IL-2 or IFN-γ or PMA/I, and the levels of TNF-α secretion were determined after 12 to 18 h." (PMID 33672708, 2021). "Th1 cytokines are structurally related to IL-2, IFN-γ, and TNF-α, whose polymorphisms are possibly associated with periodontitis risk." (PMID 35046930, 2021). "NLRP3 and IL1B genotypes and IL2 Haplotype Frequency Distributions in patients with periodontitis and controls." (PMID 31978095, 2020). "Among the several inflammatory mediators that orchestrate the periodontitis, there is the interleukin (IL)-2." (PMID 32075624, 2020). "IL1alpha, IL1beta and IL17A, and their ratios with IL2, are excellent diagnostic biomarkers in GCF for distinguishing periodontitis patients from periodontally healthy individuals." (PMID 30573746, 2018). "Chronic inflammation induced by P. gingivalis and P. intermedia and other bacteria in the oral cavity results in periodontitis that can affect both cellular and humoral immunity, with consequent release of cytokines such as IL-2, IFN-γ, and TNF-α." (PMID 29109737, 2017). "With regard to periodontitis, there has long been evidence that serum IL-2 may be an indicator of disease activity in periodontitis as higher levels of IL-2 are observed in these patients." (PMID 38541692, 2024). "The rationale behind those hypotheses was that patients with periodontitis exhibit higher systemic levels of inflammatory mediators such as interleukin (IL-2, IL-6) and tumor necrosis factor (TNF-α)." (PMID 37735212, 2023). "Unlike those from healthy individuals, OBMC-derived supernatants from periodontitis patients exhibited decreased ability to induce secretion of IFN-γ by allogeneic healthy PBMCs treated with IL-2, while they triggered significant levels of TNF-α, IL-1β and IL-6 by untreated PBMCs." (PMID 33672708, 2021). "In addition, the polymorphisms in NLRP3, IL1R, TNF, IL6, IL2, IL4 and IL4RA genes were associated with periodontitis in the males." (PMID 31978095, 2020). "In addition, the increase in IL-2 in this study implies that the role of IL-2 in the chemoresistance modulation of oral cancer cells that accompanies chronic periodontitis should be further investigated." (PMID 31117164, 2019). "IL‐2 also promotes the growth of effector T cells, including pro‐inflammatory subsets such as Th1 and Th17 cells, which could potentially exacerbate inflammation in periodontitis." (PMID 41399014, 2025). "These evidences taken together may highlight the real role of IL-2 during periodontitis." (PMID 32075624, 2020).
periodontitis (continued). "Inactivation of IFN-γ and IL-2 by gingipains from P. gingivalis at inflammatory sites could also downregulate TH1 responses (associated with nonaggressive periodontal lesions) and promote TH2 pathways and polyclonal B-cell activation in advanced periodontitis." (PMID 25530681, 2014). "GO enrichment analysis of these genes indicated that the development of periodontitis might involve biological processes, such as lymph vessel morphogenesis, regulation of metaphase plate congression, vesicle transport along microtubules, and regulation of interleukin-2 production." (PMID 41333919, 2025). "IL‐2, ATRA, IL‐33, and chemokine pathways like CCL22 offer promising strategies for enhancing Treg function and restoring immune balance in periodontitis." (PMID 41399014, 2025). "In patients with severe periodontitis, the serum concentrations of pro‐inflammatory cytokines such as IFN‐γ, IL‐2, TNF‐α, and IL‐1β are much higher than that of healthy controls, which is also observed in gingival tissue biopsies." (PMID 37647428, 2023). "In patients with periodontitis, the present study observed increased levels of pro-inflammatory factors IFN-γ, IL-1β, IL-2, IL-7, IL-21, and TNF-α, in addition to decreased levels of anti-inflammatory factors IL-5 in GCF of T2DM patients." (PMID 33417619, 2021). "The most important finding was that anti-inflammatory cytokines IL-2, IL-4, and IL-11 levels in GCF of aggressive periodontitis cases were lower compared to chronic periodontitis subjects." (PMID 34104811, 2021). "There were also detectable levels of other inflammatory mediators such as TGF-β1, IL-1β, IL-2, IL-4, IL-10, IL-12p70, and IL-17A in the GCF samples of periodontitis patients." (PMID 34502071, 2021). "When CD16 + NK and CD8+ T cells were treated with IL-2 and PMA/I, higher intensity of CD69 was detected both in OBMCs and PBMCs of periodontitis patients, although the intensity remained higher in OBMCs." (PMID 33672708, 2021). "In the present study, other ratios such as IL17A/IFNgamma, IL17A/IL2, IL17A/IL3 and IL17A/IL4 had significantly higher values in the periodontal patients, reflecting their impact on chronic periodontitis." (PMID 30573746, 2018). "Curiously, however, our results were contrary to those reported by these authors, as four anti-inflammatory cytokines (IFNgamma, IL2, IL3 and IL4) showed significantly higher concentrations in chronic periodontitis than in health." (PMID 28912468, 2017). "In addition to IL-1β, levels of IL-2, IL-8, and IL-13 were significantly elevated in the GCF of periodontitis sites compared to healthy and gingivitis sites (p < 0.05)." (PMID 41303313, 2025). "Also, it decreased the serum expressions of TNFα and IL-2 and the tissue expression of MMP-2 and -9 in the periodontitis-induced model (p < 0.05)." (PMID 37378834, 2024). "As found in the present study, in T2DM patients with periodontitis, statins treatment reduced pro-inflammatory factors IFN-γ, IL-1β, IL-2, IL-6, IL-7, IL-21 and TNF-α levels in GCF, and enhanced anti-inflammatory factors IL-4 and IL-5 levels through the anti-inflammation and anti-oxidation effects." (PMID 33417619, 2021). "We observed increased secretion of TNF-α in OBMCs from periodontitis patients with and without IL-2 or IFN-γ treatment." (PMID 33672708, 2021). "In patients with periodontitis, lower levels of pro-inflammatory factors IFN-γ, IL-1β, IL-2, IL-6, IL-7, IL-21, TNF-αand higher levels of anti-inflammatory factors IL-4 and IL-5 in gingival crevicular fluid in the Sp group were identified than those in the Dp group." (PMID 33417619, 2021). "The administration of anakinra to the periodontitis tumor bearing model also had appreciable level of MDSC and some macrophage in the neck area, but the expression of the immune-suppressive cytokines was (IL-2, IL-10, and TGF-ß) was diminished." (PMID 31685946, 2020).